CXCL12 (C-X-C motif chemokine ligand 12)
Diseases named in the same sentence as CXCL12 in open-access papers (continued):
Sharing a sentence is not in itself a finding about the gene and the disease.
myeloma (103 papers, 2011 to 2026). "Elevated serum levels of CXCL12 were found to be associated with increased osteoclast formation and bone loss in myeloma patients, and that targeted disruption of the CXCL12/CXCR4 axis inhibited osteolysis in a murine model of myeloma-associated bone loss." (PMID 37240298, 2023). "CXCL12 expression is higher in myeloma BM compared with healthy BM and cancer-associated fibroblasts (CAFs) from patients with active MM produce higher levels of CXCL12 compared from non-active MM, MGUS, and healthy subjects." (PMID 35064098, 2022). "Among all dysregulated immune-related mRNAs, AEN, CD320, FABP5, and GPI were risk factors for multiple myeloma, while CXCL12, IGKC, NOD2, VCAM1, and WNT5A were protective factors for multiple myeloma." (PMID 34249967, 2021). "CXCR4/CXCL12 blockade results in a decreased tumor cell proliferation and survival and, importantly, in the loss of myeloma cells ability to colonize the BM in vivo." (PMID 30154786, 2018). "The CXCL12-3'A variant has been demonstrated to be associated with multiple myeloma, acute lymphoblastic leukemia, various tumors, and the outcome of human immunodeficiency virus infection." (PMID 24950177, 2014). "The secretion of SDF-1 (CXCL12) from the bone marrow microenvironment contributes to the upregulation of VLA-4 expression on myeloma cells which increases their ability to bind to the extracellular matrix." (PMID 40296907, 2025). "For example, CXCL12 promotes the invasion of bone by myeloma cells by stimulating MMP-9 and MT1-MMP expression." (PMID 40142155, 2025). "In accordance with independent reports, high expression of CXCL12 and DCN by myeloma cells was associated with improved OS (adj." (PMID 38598843, 2024). "MA-INA6 upregulated adhesion and retention factors (CXCL12), that, intriguingly, were highly expressed in myeloma samples from patients with longer overall and progression-free survival, but their expression decreased in relapsed myeloma samples." (PMID 38598843, 2024). "Mesenchymal stromal cells (MSCs) have been described as an important source of CXCL12 for myeloma cells." (PMID 37591845, 2023). "ChIP-on-chip data revealed that heparanase bound to regulatory regions of myeloma-related genes (i.e., CXCL12), encodes for SDF-1, CXCR4, CXCL2, CXCR3, CCL27, CX3CL1, and LCN2." (PMID 36980254, 2023). "For example, CXCL12 can be expressed in the bone marrow (BM) and promote the migration of myeloma cells." (PMID 35893797, 2022). "For example, we have recently employed this platform to conduct successful loss-of-adhesion CRISPR screens for integrin α4β1-mediated adhesion of multiple myeloma cells to VCAM-1 upon stimulation of the chemokine receptor CXCR4 with the chemokine CXCL12." (PMID 35440579, 2022). "The resulting CX43/CXCL12/CXCR4 interplay enhances mitochondrial trafficking from MSCs to myeloma PCs and can protect cancer cells against anti-myeloma agents." (PMID 35064098, 2022). "The CXCR4/CXCL12 axis plays a crucial role in multiple myeloma (MM) cells homing to the bone marrow and the interaction between the bone marrow microenvironment and MM cells." (PMID 35056696, 2022). "Multiple CD45-silenced myeloma cells completely lost their migratory potential in response to CXCL12." (PMID 35682990, 2022). "Thymoquinone decreased the surface expression of CXCR4 on multiple myeloma cells and CXCL12-mediated CXCR4-CD45 interactions." (PMID 35682990, 2022). "S1PR1 depleted myeloma cells retained full CXCL12 responsiveness while CXCR4 depleted myeloma cells were unable to induce CXCL12-stimulated cell adhesion or transendothelial migration after S1P stimulation." (PMID 35756630, 2022). "For a detailed study of multiple myeloma, a microfluidic system imitating BM stromal and sinusoidal endothelium components, as well as sinusoidal circulation, made it possible to study CXCL12-mediated egress of myeloma cells from BM stroma." (PMID 35457280, 2022).
myeloma (continued). "In multiple myeloma, tumor cell-derived CXCL12 stimulates bone resorption, providing a potential explanation for the positive correlation between CXCL12 plasma levels and osteolytic lesions in affected patients." (PMID 34064859, 2021). "A study on myeloma found that CXCL12, a key molecule involved in CXCR4-dependent cell retention in bone marrow, was upregulated in circulating plasma cells and potentially induced myeloma cells’ intravasation." (PMID 33802312, 2021). "CXCL12 is a target for reversing cellular adhesion-induced drug resistance against multiple myeloma." (PMID 34249967, 2021). "The survival and proliferation of multiple myeloma (MM) cells in the bone marrow (BM) critically depend on interaction with stromal cells expressing the chemokine CXCL12." (PMID 33436043, 2021). "Activation of this receptor by CC motif chemokine ligand 3 (CCL3) reduces the response of multiple myelomas to CXCL12 and the consequent egress of these cells from bone marrow." (PMID 33467722, 2021). "As recently reported, CXCL12 favors a pro-metastatic bone marrow niche in multiple myeloma, as well as in solid tumors with propensity to give bone metastases, including gastric, medullary thyroid, lung, prostate, and renal carcinomas." (PMID 32719743, 2020). "Inhibition of S1P signaling using fingolimod in multiple myeloma revealed that metastasis to the bone marrow was due to the C-X-C chemokine receptor 4 (CXCR4)/C-X-C motif chemokine 12 (CXCL12) pathway." (PMID 32977496, 2020). "In vivo, olaptesed-pegol neutralize CXCL12, leading to a bone marrow microenvironment that is less receptive for multiple myeloma cells and reduces multiple myeloma cell homing and growth." (PMID 33363463, 2020). "In a recent study, CXCL12 produced by both the multiple myeloma (MM) cells and bone marrow stromal cells (BMSCs) was found to regulate monocyte migration." (PMID 33363463, 2020). "The inhibition of CXCL12 reduced the myeloma-supportive activity of the bone marrow microenvironment and mobilized myeloma cells into the circulation." (PMID 31878087, 2019). "Olaptesed pegol (NOX-A12) is a pegylated L-oligoribonucleotide that binds and neutralizes CXCL12, achieving the mobilization of myeloma cells for at least 72 h and enhancing the activity of dexamethasone without relevant additional toxicity (NCT04121455)." (PMID 31878087, 2019). "Multiple myeloma cells recruit tumor-supportive macrophages through the CXCL12/CXCR4 axis and promote their polarization toward M2 phenotype." (PMID 30678736, 2019). "In the MM environment, blood-derived monocytes are recruited to the marrow by myeloma derived c-x-c motif chemokine 12 (CXCL12) and become a pro-tumor macrophage phenotype." (PMID 30405034, 2018). "Receptor downregulation was correlated with reduced CXCL12-mediated invasion of multiple myeloma cells after 24 hours incubation with gambogic acid." (PMID 28410420, 2017). "A decrease in NK cell numbers in the bone marrow of patients with myeloma has been shown to correlate with a decrease in the chemokine CXCL12 and an upregulation of CXCR3 ligand expression." (PMID 28389623, 2017). "Chemokine gradients are of central importance and there are data showing the importance of an upregulated CXCR4/CXCR7/CXCL12 axis in driving recruitment of tumour cells into the bone marrow in patients with multiple myeloma." (PMID 28389623, 2017). "CXCL12 neutralization in vivo within BM niches renders the BM less receptive and thus reduced homing, growth, and disease progression as shown for multiple myeloma cells." (PMID 28423491, 2017). "In contrast, targeting chemokine/receptor crosstalk is feasible and therapeutically relevant, as has been shown e.g. for CXCL12/CXCR4 also in myeloma." (PMID 27732933, 2016). "In our 3D model, we observed significantly higher expression of CXCL12 on myeloma derived-MSCs and upregulated CXCR-4 expression on plasma cells, as well as significant production of sTie-2 receptor and SCF, reflecting the MM niche." (PMID 27764795, 2016).
myeloma (continued). "The presence of high levels of CXCR4 and CXCR7 receptors in monocytes led us to study the possible role of the corresponding chemokine ligand, CXCL12, in myeloma-induced monocyte recruitment." (PMID 25526031, 2014). "In a murine model of multiple myeloma, CXCL12 secreted by the BM-invading multiple myeloma cells, recruited osteoclasts to the tumor vicinity and activated them, leading to bone loss." (PMID 24276423, 2013). "In multiple myeloma, therapeutic strategies should focus on reversing the tumor-supportive phenotype of mesenchymal stem cells, potentially via targeted inhibition of IL-6 or CXCL12 signaling." (PMID 40140850, 2025). "This CCR1-CCL3 interaction inhibits myeloma cell migration towards CXCL12." (PMID 40296907, 2025). "The bone marrow microenvironment plays a crucial role in the progression of multiple myeloma by secreting a range of cytokines and growth factors (e.g., IL-6, VEGF, TGF-β, IGF-1, CXCL12) that support the survival, proliferation, and resistance to apoptosis of myeloma cells." (PMID 38831183, 2024). "In addition to bone marrow stromal cells, circulating plasma cells in multiple myeloma also produce CXCL12 and the high levels of CXCL12 in this disease are involved in various pathological processes." (PMID 37240298, 2023). "Based on this knowledge and their own discoveries, Garcia-Bernal and colleagues proposed that S1P gradients from blood to BM niches with low CXCL12 may constitute a mechanism facilitating myeloma cell egress from BM for metastasis to other tissues." (PMID 35756630, 2022). "CXCL12 induced a physical association between CXCR4 and CD45 in multiple myeloma cells." (PMID 35682990, 2022). "Furthermore, plerixafor, a selective inhibitor of CXCR4, significantly reduced mitochondrial transfer from MSCs to myeloma PCs further establishing mechanistically that CXCR4/CXCL12 is directly involved in mitochondrial trafficking." (PMID 35064098, 2022). "Our data further pointed out that CXCR4/CXCL12 pathway may serve as a new strategy to target myeloma niche." (PMID 35064098, 2022). "Taken together, our data demonstrated that CXCL12/CXCR4 axis mediates intercellular coupling thus suggesting that the myeloma niche may be exploited as a target to improve and develop therapeutic approaches." (PMID 35064098, 2022). "BKT140 reduces the growth of acute myeloid leukemia and multiple myeloma, disrupts the CXCL12-mediated adhesion of tumor cells to stromal cells to improve the efficacy of radiotherapy and chemotherapy in lung cancer, and plays a prominent role in the treatment of lymphoma." (PMID 35893797, 2022). "Multiple myeloma cells show increased CXCL12 production upon interaction with bone marrow stromal cells, thus promoting the recruitment and polarization of M2 TAMs, and subsequently changing the immune status of the tumor towards a more immunoevasive phenotype." (PMID 33530455, 2021). "Activation of this receptor reduces the action of CXCL12 on multiple myeloma cells." (PMID 33467722, 2021). "Furthermore, it has been demonstrated that CXCL12 is highly expressed by MM-MSCs at BM sites of metastatic disease showing a major role in directing homing and trafficking of myeloma PCs." (PMID 34067236, 2021). "Among them, CXCL12 up-regulation could be induced by HIF-2α in multiple myeloma plasma cells, thereby reducing migration as well as adhesion to mesenchymal stromal cells." (PMID 34249967, 2021). "The CXCR4/CXCL12 axis has been described to regulate the localization of NK cells in the bone marrow and seems to be of importance with respect to recruitment of NK cells to the tumor site in neuroblastoma and multiple myeloma." (PMID 31457007, 2019). "We noted that CSL treatment can indeed inhibit the CXCL12-induced myeloma cell migration." (PMID 29773987, 2018). "We recently showed that the expression of CXCR4 and CXCL12 in multiple myeloma cells is positively regulated by Notch signaling and may be impaired by γ-secretase inhibitors." (PMID 30154786, 2018).
myeloma (continued). "Furthermore, it has been shown that S1P/S1P1 interactions enhance the CXCL12-mediated myeloma cell adhesion to fibronectin through VLA-4 (the α4β1 integrin) and VLA-4-mediated transendothelial migration." (PMID 29757216, 2018). "CXCR4 and its ligand CXCL12 are important in the migration of cells to the lymph nodes in acute lymphoblastic leukemia and chronic lymphocytic leukemia, they are also an important factor for migration of myeloma cells to the bone marrow." (PMID 24859274, 2014). "In this work the authors confirmed that myeloma cells with lower expressions of CD54 were more susceptible to apoptosis and the addition of CXCL12 to the in vitro culture significantly induced the up-regulation of CD54 expression in primary myeloma cells, promoting their survival." (PMID 23251606, 2012). "In that study, serum levels of TWEAK correlated with the serum bone resorption marker, β-crosslaps, and levels of the osteoclast recruitment chemokine, CXCL12, strongly implying a pathological role for plasma cell-derived TWEAK in bone erosion associated with multiple myeloma." (PMID 21435232, 2011). "Therefore, we moved to co-culture HS-5 cells with U266 or NCI-H929 myeloma cell lines to evaluate whether tumor cells were able to increase the levels of both CXCL12 and CX43 in healthy MSCs." (PMID 35064098, 2022). "Importantly, by blocking either IL-3 or CXCL12, myeloma cell growth was markedly abrogated." (PMID 33562441, 2021). "Similarly, decreased levels of CXCL12 in BM plasma samples from a cohort of patients with active multiple myeloma as compared with a premalignant stage support the hypothesis of a reduced NK cell surveillance based on reduced BM recruitment." (PMID 27766097, 2016). "Likewise, the CXCR4 antagonist TG-0054 (Burixafor, ChemoCentryx) and the aptamer Nox-A12 (Spiegelmer, Noxxon), an anti-CXCL12/SDF-1, are currently being tested in clinical trials in combination with chemotherapy for multiple myeloma and for chronic lymphatic leukaemia." (PMID 26062132, 2015). "This prevents interaction of CXCR4 with CXCL12 which further reduces α4β1 (VLA-4) and VCAM-1 activation, promoting myeloma cell exit from bone marrow." (PMID 40296907, 2025). "Human bone marrow–derived mesenchymal stromal cells (hMSC) stimulate myeloma cell expansion (e.g., IL6) and simultaneously retain myeloma cells via chemokines (e.g., CXCL12) and adhesion factors." (PMID 38598843, 2024). "SERPINE1 (together with ANGPTL4, GDF15, CXCL12, SOX9, HOXB6, and ANK3) was even described as a TA-MSC factor, namely, in mesenchymal stromal cells of the bone marrow that supported myeloma cell growth." (PMID 39011489, 2024). "Chemokine (C-X-C motif) ligand 12(CXCL12), chemokines ligand 2(CCL2), chemokines ligand 3(CCL3) and chemokines ligand 14(CCL14) produced by myeloma cells and BMSCs promote macrophage M2 polarization and imbalance the M1/M2 ratio." (PMID 37275861, 2023). "CXCL12 and its receptor CXCR4 represent a critical communication axis between MSCs and tumor PCs to promote the expansion and colonization of myeloma PCs in the BM." (PMID 35064098, 2022). "CXCL12 is the ligand of CXCR4 and mediates the homing mechanisms of both healthy and myeloma PCs into the BM." (PMID 35064098, 2022). "AMD3100 is the only marketed CXCL12/CXCR4 antagonist and was approved by the FDA in 2008 for autologous transplantation in patients with non-Hodgkin’s lymphoma (NHL) and multiple myeloma (MM)." (PMID 35893797, 2022). "Notch positively controls CXCL12/CXCR4 function in myeloma cell lines, and in vivo blockade of Notch markedly limits myeloma cell infiltration into bone marrow of mouse xenografts." (PMID 35702353, 2022). "Interaction of myeloma cells and bone marrow stromal cells (BMSCs) upregulates the production of C-X-C motif chemokine ligand 12 (CXCL12), leading to increased recruitment of human monocytes expressing C-X-C motif chemokine receptor 4 (CXCR4) to myeloma TME." (PMID 34359674, 2021).
myeloma (continued). "In the GSE4204 dataset, our Kaplan-Meier survival analyses demonstrated that low expression of CXCL12 (p-value: 0.009800177) and WNT5A (p-value: 0.012647237) displayed more unfavorable outcomes for multiple myeloma patients." (PMID 34249967, 2021). "Finally, in multiple myeloma (MM) cells, CXCR4 expression correlated with disease progression, chemotherapy resistant MRD, and poor prognosis, while an increase in the CXCL12 serum expression level was associated with increased osteolytic disease and increased BM angiogenesis." (PMID 32260318, 2020). "CXCL12 is known to transactivate EGFR, the axis CXCR4/CXCL12 is upregulated in HCC and participates in HCC cell proliferation and BKT140 has been tested in clinical trials for the treatment of multiple myeloma." (PMID 24212818, 2011). "However, many clinical trials have been halted due to severe side effects due to CXCL12 antagonism and the main CXCR4 antagonist used in the clinic is AMD3100 to boost stem cell mobilization in lymphoma and myeloma patients." (PMID 39737176, 2024). "Together, the expression of adhesion or BM retention–related markers (CXCL12, DCN, and TGM2) is reduced or lost at advanced stages of multiple myeloma, which could enhance dissemination and reduce retention in the BM microenvironment." (PMID 38598843, 2024). "Since both S1P and CXCL12 activate DOCK2–Rac1 signaling that controls α4β1 affinity, the authors suggest that S1P amplifies CXCL12-activated myeloma cell adhesion by further stimulating or maintaining high-affinity α4β1 conformations at early cell attachment steps." (PMID 35756630, 2022). "After CXCL-12 and CXCR4 binding, the homing of myeloma cells and osteoclastogenesis are triggered." (PMID 35328533, 2022). "In MCL, as well as other hematological malignancies, such as chronic lymphocytic leukemia and myeloma, CXCR4/CXCL12 is known to mediate tumor cell migration (“homing”) and adhesion to bone marrow stromal cells, which function as a protective microenvironment 6-9." (PMID 33391493, 2021). "Another successful aptamer therapeutic is NOX-A12, a spiegelmer—an unnatural mirror image nucleic acid aptamer strand—which targets CXCL12/SDF-1, a key chemokine involved in the maintenance of the tumor microenvironment in chronic lymphocytic leukemia and multiple myeloma cancers." (PMID 32848740, 2020). "Previous studies using the myeloma 5TMM mouse model demonstrated the involvement of the CXCL12/CXCR4 axis in the homing and progression of MM, and revealed the reduction of both processes by in vivo neutralization of CXCL12 with olaptesed-pegol (NOX-A12)." (PMID 30787933, 2019). "The interaction between Notch, CXCL12, and CXCR4 might also have a further outcome since high CXCL12 levels in the multiple myeloma niche increase the M2 macrophage population in the immune cell infiltrate." (PMID 30154786, 2018). "Conversely, disruption of the CXCL12/CXCR4 interaction has been shown to promote hematopoietic stem cell mobilization, promoting immunologic response of patients with non-Hodgkin lymphoma and multiple myeloma." (PMID 28055968, 2017). "The role of CXCR4/CXCL12 axis has been proved also in hematopoietic neoplasms, such as acute lymphoblastic leukemia (ALL), acute myeloid leukemia (AML), chronic lymphocytic leukemia (CLL), multiple myeloma (MM) and Waldenström Macroglobulinemia (WM)." (PMID 24859274, 2014). "Moreover, CXCL12 supports MM growth through the induction of interleukin-6 (IL-6) and vascular endothelial growth factor (VEGF) secretion and increases invasion and matrix metalloproteinase (MMP) secretion in myeloma PCs." (PMID 35064098, 2022). "In view of these dual roles of CXCL12, it is expected that the CXCL12-CXCR4 pair will be instrumental in regulating osteoclastogenesis and osteolysis in tumors, but currently this aspect was mainly investigated in multiple myeloma and needs to be extensively addressed in future studies." (PMID 32582148, 2020).